CPEB4 (cytoplasmic polyadenylation element binding protein 4)
Diseases named in the same sentence as CPEB4 in open-access papers (continued):
Sharing a sentence is not in itself a finding about the gene and the disease.
ovarian carcinoma (1 paper, 2020). A malignant neoplasm originating from the surface ovarian epithelium. "Overall, these results suggest that the upregulation of CPEB4 was associated with functional resistance of ovarian cancer cells to paclitaxel and is impossibly due to acute inducible effect of paclitaxel in naive sensitive cells." (PMID 33519462, 2020). "Collectively, these data indicate that CPEB4 is upregulated in paclitaxel-resistant ovarian cancer cells and recurrent ovarian tumors, and also imply an association of its upregulation with paclitaxel resistance." (PMID 33519462, 2020). "In functional studies, we found that CPEB4 promoted paclitaxel resistance in ovarian cancer cells in vitro." (PMID 33519462, 2020). "In this study, we report that CPEB4 promotes paclitaxel resistance in ovarian cancer, and suggest that this effect depends on its translational regulation of CSAG2." (PMID 33519462, 2020). "Together, these lines of evidence prove that CPEB4 upregulation promotes paclitaxel resistance in ovarian cancer cells in vitro." (PMID 33519462, 2020). "In despite of the largely unclear role of CPEB4 in ovarian cancer progression, our study reveals its connection to paclitaxel resistance in ovarian cancer." (PMID 33519462, 2020). "In addition, CPEB4 overexpression promotes paclitaxel resistance in ovarian cancer cells in vitro, and vice versa, CPEB4 knockdown restores paclitaxel sensitivity, indicating that CPEB4 confers paclitaxel resistance in ovarian cancer cells." (PMID 33519462, 2020). "We then asked whether CSAG2 mediates the promotive effect of CPEB4 on paclitaxel resistance in ovarian cancer cells." (PMID 33519462, 2020). "To explore whether CPEB4 plays a role in paclitaxel resistance in ovarian cancer, we compared its transcript levels between naive sensitive SKOV3 (S) cells and their paclitaxel-resistant counterparts SKOV3 (R) through qRT-PCR analysis." (PMID 33519462, 2020). "Consistently, similar tendency was obtained when examining the effect of CSAG2 knockdown on CPEB4-mediated advantages for colony formation, further strengthening the notion that CSAG2 at least in part contributes to CPEB4-mediated paclitaxel resistance in ovarian cancer." (PMID 33519462, 2020). "Another critical issue needs to be addressed is whether CPEB4-regulated paclitaxel resistance via CSAG2 in ovarian cancer can be reproduced with in vivo scenarios." (PMID 33519462, 2020). "Thus, interfering CPEB4/CSAG2 axis might be of benefit to overcome paclitaxel-resistant ovarian cancer." (PMID 33519462, 2020). "Moreover, CSAG2 expression is upregulated in paclitaxel-resistant ovarian carcinoma and cancer cell lines, and more importantly, siRNA-mediated CSAG2 knockdown overtly attenuates CPEB4-mediated paclitaxel resistance." (PMID 33519462, 2020). "The stable overexpression of CPEB4 did not obviously affect cell proliferation or survival, however, it markedly increased the survival rate of both two ovarian cancer cell lines when treated with paclitaxel." (PMID 33519462, 2020).
ovarian tumors (1 paper, 2020). "Next, we performed immunohistochemistry to compare CPEB4 expression between paired primary untreated ovarian tumors and recurrent tumors treated with paclitaxel-based chemotherapy." (PMID 33519462, 2020). "The transcript level of CPEB4 in these paired tumors was also quantified, and likewise, significant upregulation of CPEB4 was observed in recurrent ovarian tumors." (PMID 33519462, 2020). "The result showed that CPEB4 had stronger immunoreactive staining in recurrent tumors than that of primary tumors (left), and semi-quantification using H-score analysis proved the higher expression level of CPEB4 in recurrent ovarian tumors (right)." (PMID 33519462, 2020).
Parkinson disease (1 paper, 2024). A progressive degenerative disorder of the central nervous system characterized by loss of dopamine producing neurons in the substantia nigra and the presence of Lewy bodies in the substantia nigra and locus coeruleus. "The SAES-correlated gene CPEB4, exhibiting RNA binding activity, is within an IBD GWAS locus, and autoantibodies against ribosomal protein RPS18 are potential biomarkers for early-stage Parkinson's disease." (PMID 39165421, 2024).
periodontitis (1 paper, 2023). An acute or chronic inflammatory process that affects the tissues that surround and support the teeth. "CPEB1 and CPEB4, another periodontitis risk gene, are essential for successful mitotic cell division and have sequential nonredundant functions." (PMID 37822091, 2023).
renal cell carcinoma (1 paper, 2021). "However, the functional roles of CPEB4 in Renal cell carcinoma (RCC) are still unclear." (PMID 34976999, 2021).
cancer (29 papers, 2012 to 2026). A tumor composed of atypical neoplastic, often pleomorphic cells that invade other tissues. "Abnormal expression of CPEB4 is associated with certain types of cancer, suggesting that CPEB4 can play critical roles in the control of cancer proliferation and metastasis." (PMID 33237662, 2021). "CPEB4 is significantly upregulated in various types of tumors and is of paramount importance for fine-tuning the synthesis of proteins implicated in the malignancy of cancer cells." (PMID 34781999, 2021). "In cancer, CPEB4 is often overexpressed and acts as an oncogene, promoting the translation of proteins that drive tumor growth, blood vessel formation (angiogenesis), and metastasis." (PMID 41596407, 2026). "We found that the expression of CPEB4 was lower in cancer cells, consistent with the results in HNSCC and NPC tumor tissue (as reported in our previous research)." (PMID 40084246, 2025). "Additional genes upregulated in carcinoma patients as a result of CARD11 overexpression included MTMR2, EMB, EPHB6, and CPEB4, which are related to various cancer-related processes." (PMID 39408697, 2024). "RP11-361F15.2 acts as an oncogenic factor that promotes CPEB4-mediated cancer cell migration and invasion by binding to miR-30c-5p and increasing CPEB4 protein levels." (PMID 36263199, 2022). "In particular, it is suggested that CPEB4 plays an important role in the migration and invasion of cancer cells in certain types of cancer, and can be used as a target for cancer treatment." (PMID 33237662, 2021). "Future studies need to explain the reasons for the contradictory roles of CPEB4 in different cancers." (PMID 34976999, 2021). "Worthy of note, TIA1 is the only RBP that suppresses the ability of cancer cells to escape immune response by enhancing NK cell cytotoxic activity; also, CPEB4 is the only RBP that promotes genome instability by influencing chromatin-remodeling." (PMID 31440515, 2019). "Taken together, downregulation of CPEB4 likely occurs at the late cancer stage to facilitate HCC progression." (PMID 27158894, 2016). "CPEB4 was also attractive as in cancer, this is the only CPEB for which antibodies have been validated for genome-wide RNA immunoprecipitation and target identification." (PMID 27857118, 2016). "Thus, stage-associated alteration in CPEB4 expression may also apply to other cancers besides HCC." (PMID 27158894, 2016). "Nevertheless, the identification of the exact signaling pathway and the best use of CPEB4 as a marker to stratify cancer patients for personalized treatment remain critical goals." (PMID 26166131, 2015). "In summary, CPEB4 is a critical molecular switch for protein synthesis, essential for brain function and development, but when dysregulated, it becomes a key player in diseases like cancer and autism." (PMID 41596407, 2026). "Notably, CPEB4 plays a critical role in modulating cancer cell sensitivity to ferroptosis, a form of regulated cell death driven by iron-dependent lipid peroxidation." (PMID 40732992, 2025). "So far, CPEB4 was primarily known as part of an activator complex that enhances translation via poly(A) tail lengthening of selected target mRNAs during meiotic and mitotic cell division, cancer progression and neurodevelopment." (PMID 36096941, 2022). "Whether the contradictory role of CPEB4 in different cancer is related with the alternative splicing of CPEB4 remains to be further investigated in the future." (PMID 34976999, 2021). "After that, CPEB4 expression was found aberrantly expressed in several cancers." (PMID 34976999, 2021). "CPEB4 seems to play paradoxical roles in different cancers, and the expression and function of CPEB4 in RCC remains unknown." (PMID 34976999, 2021).
cancer (continued). "It was further shown that CPEB4 be highly involved in cancer progression." (PMID 31581661, 2019). "Depending on the cancer type and stage, CPEB4 may switch its role between oncogenic promoter and tumor suppressor." (PMID 27158894, 2016). "Whether CPEB4 functions as an oncogenic promoter or suppressor in early-stage HCC and whether CPEB4 could be a diagnostic marker and/or therapeutic target in cancers need to be further investigated." (PMID 27158894, 2016). "Carcinoma patients showed a dramatic increase in the expression of MAPK8IP2 in CARD11+ carcinoma patients alongside other cancer-related genes, including EMB, EPHB6, and CPEB4." (PMID 39408697, 2024). "There are approximately 98.2% methylation-regulated genes shared by at least two types of cancers, including 3,801 genes (e.g., HIST1H4F, FBP1 and CPEB4) shared across all cancers." (PMID 34464378, 2021). "Cytoplasmic polyadenylation element-binding protein 4 (CPEB4) has been reported to be dysregulated in a variety of cancers and seems to play paradoxical roles in different cancers." (PMID 34976999, 2021). "Our yeast two-hybrid screen identified an interaction between CPEB4 and ATOX1 which calls for further investigation of putative synergistic cancer-promoting effects between these proteins." (PMID 28425924, 2017). "Of the rest, CPEB4, MCM4, RNF4, STAT2, and WEE1 were also shown to correlate with a number of cancer types." (PMID 27418131, 2016). "However, the exact CPEB4 signaling pathway that is involved in cancer progression remains unknown." (PMID 26166131, 2015). "Garcia-Pras and colleagues observed that mesenteric CPEB4 levels correlate spatiotemporally with VSPC expansion and neovascularization under PHT circumstances, and in vitro studies determined that CPEB4 is critical for cell division, SPC function and pathological angiogenesis in cancer and PHT." (PMID 34912244, 2021). "However, we know considerably less about CPEB3’s role in cancer development compared with the body of work available for CPEB1 and CPEB4." (PMID 33146632, 2020). "Additionally, Hu et al18 found that CPEB4 was strongly induced by the important erythroid-related transcription factors Gata1 and Tal1 and that 1 CPEB4 target gene is CDK6, an important protein in cell cycle regulation and cancer development." (PMID 26166131, 2015). "While CPEB4 is physiologically expressed in the brain, heart, kidney and lung, it has been the most related CPEB to HCC, although its role comes as quite paradoxical; whilst it seems to play a tumor-suppressor role in HCC, it’s been described as an oncogenic promoter in other kinds of cancer." (PMID 34912244, 2021). "The other possibility is that CPEB4 may affect mitotic entry in cancer cells but not in normal cells." (PMID 24386439, 2013).
tumor (29 papers, 2015 to 2025). "Among all the genes reported in the literature with their potential cause in tumor development, CPEB4, APC, TRIP13, EIF2S3, EIF4A1, IFNg, PIK3CA and CTNNB1 have particularly been identified to be a set of potential candidates for tumor development." (PMID 33237662, 2021). "Cytoplasmic polyadenylation element binding (CPEB4) is a RNA binding protein and a part of the CPEB family, and increased CPEB4 expression is implicated in migration, tumor growth, vascularization, metastasis and invasion." (PMID 31770107, 2019). "CPEB4 is associated with a large number of CPE-containing mRNAs that are potential targets for tumor-specific translational regulation." (PMID 26166131, 2015). "The poor prognosis associated with CPEB4 is linked to enhanced tumor aggressiveness." (PMID 40084246, 2025). "CPEB4 is intimately associated with the metastasis of a variety of tumours." (PMID 35317822, 2022). "To determine whether the higher CPEB4 levels in tumour cells caused the specificity of cB1-3′-UTR regulation of mRNA translation, we first confirmed the specificity of CPEB4 binding to the CPEs in cB1-3′-UTR." (PMID 28300077, 2017). "Deregulation of CPEB1 and CPEB4 have been linked to tumor development." (PMID 26398195, 2015). "Thus, detecting CPEB4 expression in CRC tissues or peripheral blood might be used as an additional parameter to identify patients with a high risk of tumor invasiveness and/or metastasis." (PMID 31440515, 2019). "Thus, although both CPEB1 and CPEB4 have been linked to cell proliferation and tumor development, the evidence is conflicting as to whether they act as tumor suppressors or oncogenes based on their role in cell cycle progression." (PMID 26398195, 2015). "Subsequently, we reviewed extensive data to understand the contradictory findings 15, 18, focusing on factors like CPEB4's role in embryonic development and its regulation in normal and tumor tissues." (PMID 40084246, 2025). "β-catenin inhibitors effectively block CPEB4's tumor-promoting effects, making them potential targets for therapeutic intervention." (PMID 40084246, 2025). "Surprisingly, overexpression of CPEB4 in tumor cells resulted in enhanced malignant behaviors, including proliferation, invasion, and migration." (PMID 40084246, 2025). "In vivo experiments confirmed that CPEB4 overexpression promoted tumor invasiveness and migration, effects that were effectively suppressed by β-catenin inhibitors." (PMID 40084246, 2025). "Our subsequent experiments, focusing on NPC cells and transplanted tumor models in nude mice, investigated how CPEB4 overexpression promotes malignant tumor phenotypes." (PMID 40084246, 2025). "In vivo experiments demonstrated that CPEB4 overexpression promotes tumor growth, while β-catenin inhibitors reduce tumor size in mice." (PMID 40084246, 2025). "In cellular experiments, we observed reduced CPEB4 protein levels in tumor cells compared to normal cells." (PMID 40084246, 2025). "One possible explanation is that CPEB4, as a secreted protein, is more abundant in mononuclear macrophages, mast cells, and plasma cells within the tumor microenvironment than in tumor cells, potentially promoting a pro-tumorigenic phenotype." (PMID 40084246, 2025). "CPEB4 has been identified as playing an important role in the proliferation of tumour cells and tumour development progression." (PMID 35317822, 2022). "To validate the involvement of p21 in the CPEB4-mediated tumor-inhibiting effect, we introduced stable p21 expression into CPEB4-knockdown cells or control cells with an empty vector." (PMID 34976999, 2021). "PI3K/Akt pathway was the CPEB4 downstream signaling pathway which regulated various tumor progression." (PMID 33106913, 2021). "CPEB4 exerts an anti-tumor effect by increasing p21 mRNA stability and inducing G1 cell cycle arrest in RCC." (PMID 34976999, 2021).
tumor (continued). "CPEB4 is thought to affect tumor growth, invasion and vascularization by applying preoncogenic effects, since the high level of expression of CPEB4 has been defined in a wide variety of malignancies." (PMID 33237662, 2021). "Considering the studies, there are different results related to CPEB4 in different types of tumor tissues." (PMID 33237662, 2021). "In experiments on glioblastoma and astrocytoma cell cultures, inhibition of CPEB4 expression by siRNAs decreased invasion and migration of tumor cells." (PMID 33789753, 2021). "For example, a study has demonstrated that CPEB4 is a novel target of miR-203, and the anti-tumor influence of miR-203 was reversed via overexpression of CPEB4 in SW480 cells." (PMID 31770107, 2019). "A reverse approach, of overexpressing CPEB4 in non-tumour cells (HPDE), partially rescued the expression of E1A from AdCPE and viral replication, as compared to Adwt." (PMID 28300077, 2017). "In contrast, high CPEB4 expression levels in pancreatic ductal adenocarcinoma and glioblastoma tumours correlated with stimulation of tumour growth, angiogenesis and decreased survival." (PMID 28300077, 2017). "CPEB4 positive tumor cells often showed a strong enhancement of protein expression in cell processes." (PMID 27256982, 2016). "Cytoplasmic polyadenylation element binding protein 4 (CPEB4) is a sequence-specific RNA-binding protein and translational regulator, with expression associated with tumor progression." (PMID 27158894, 2016). "CPEB4 depletion in tumor cells has limited impact on cell proliferation but prevents growth of xenografted tumors." (PMID 26398195, 2015). "In an in vivo xenograft mouse model, CPEB4 knockdown accelerates tumor growth." (PMID 40084246, 2025). "Tumours of different tissue origins may have different expressions of CPEB4 due to tissue specificity." (PMID 39771522, 2024). "The results showed that ASEs up-regulated in BLCA with high-level neoplasm grade were enriched to several RBPs’ motifs, including “poly-T” motifs and polypyrimidine tract (Py-tract) sequence of HuR, CPEB4, TIA1, HNRNPC, PTBP1, RALY and ZC3H14, and motifs of PCBP2 and SNRNP70." (PMID 37810965, 2023). "The tumours sizes and weights in the circESRP1 overexpression vector group were significantly larger than those in the NC group, and these differences were partially reversed by cotransfection with sh-CPEB4." (PMID 35317822, 2022). "CPEB4 has low expression in brain and plays a role in promoting tumor growth and progression." (PMID 35368691, 2022). "Increasing evidence has shown that CPEB4 is involved in tumour invasion and metastasis." (PMID 35317822, 2022). "Our data showed that CPEB4 also acted as a tumor surpressor in RCC." (PMID 34976999, 2021). "In contrast, the overexpression of CPEB4 in 786O cells markedly inhibited tumor growth in vivo." (PMID 34976999, 2021). "CPEB4 significantly inhibits RCC tumor growth both in vivo and in vitro." (PMID 34976999, 2021). "Importantly, viral genome replication is dependent on CPEB4 activity and can only occur in tumour cells." (PMID 28300077, 2017). "The CPEB4 protein consists of 729 amino acids and exhibits a molecular weight of 80.2 kDa, and CPEB4 plays a key role in gene transcriptional regulation during tumor development." (PMID 26166131, 2015). "Similarly, the specific APA modification of VEGFB may be involved in the functional regulation of CPEB1 and CPEB4, further contributing to the tumorigenesis of multiple tumor types, including cervical, ovarian, and glioma cancers." (PMID 32626751, 2020). "Therefore, we questioned whether this early induction of CPEB4 reflects in the control of essential genes for cell proliferation, and to which extent these functions are shared with other tumour types." (PMID 27857118, 2016).